CHEK2 (checkpoint kinase 2)
Diseases named in the same sentence as CHEK2 in open-access papers (continued):
Sharing a sentence is not in itself a finding about the gene and the disease.
breast cancer (continued). "Twenty founder alleles in BRCA1, BRCA2, CHEK2, NBN, PALB2 and RECQL genes are responsible for the majority of hereditary breast cancers in Polish women." (PMID 34461861, 2021). "In our previous study, twenty recurrent mutations were found in six breast-cancer-predisposing genes (BRCA1, BRCA2, CHEK2, PALB2, NBN, and RECQL) in Polish breast cancer patients." (PMID 32824581, 2020). "In total, the panel covered about 80% of all BRCA1/2, CHEK2, PALB2, NBN, and RECQL mutation detection in Polish high-risk families with breast cancer." (PMID 32824581, 2020). "As genotoxic reagents including Eto are involved in the chemotherapy of breast cancer, we check the influence of CHEK2 and PRR14 on patients’ response to chemotherapy." (PMID 32541902, 2020). "Meanwhile, numerous studies have associated mutations in moderate-penetrance genes, including PALB2, ATM, CHEK2, BRIP1, with increased breast cancer risk of two to four-fold compared to the 10% risk of the general population." (PMID 32091409, 2020). "It is worth noting that the ovarian cancer patients harbouring ATM PV, as well as the breast cancer cases with CHEK2 PV, present a familial history matching both HNPCC and HBOC criteria." (PMID 32522261, 2020). "The median age of first cancer diagnosis was compared in monoallelic and biallelic CHEK2 PV carriers for any cancer, and for breast cancer specifically." (PMID 31993860, 2020). "The goal of the current study was to estimate the prevalence of twenty alleles in six genes, BRCA1/2, CHEK2, PALB2, NBN, and RECQL, in Polish early-onset breast cancer patients." (PMID 32824581, 2020). "Estimating these while accounting for competing risks (non-breast cancer related death) yielded 4.6%, 4.9% and 3.2% lower estimates for lifetime risks in carriers of the PALB2 and CHEK2 mutations, and women with high PRS, respectively." (PMID 33318493, 2020). "The rare missense variant c.347C>T changed the conserved amino acid p.P116L in a patient with superficial spreading melanoma and breast cancer carrying also a germline deletion of 5395bp affecting exons 9 and 10 of the CHEK2 gene (NM_007194)." (PMID 33050356, 2020). "Breast cancer was the most prevalent cancer reported in both monoallelic and biallelic carriers of CHEK2 PVs, with ovarian cancer being the second most prevalent single cancer in both." (PMID 31993860, 2020). "Susceptibility genes with high or moderate penetrance (i.e., BRCA1, BRCA2, PALB2, ATM, and CHEK2) have been identified in 30 to 40% of patients with a family history of breast cancer, but only in 5% of sporadic breast cancer cases." (PMID 33126731, 2020). "Second, we identified two deleterious alterations in CHEK2, c.593-1G > T and p.Thr476Met, in two patients who developed breast cancer, a cancer type related to PV in this gene." (PMID 32522261, 2020). "In conclusion, we show that a high breast cancer PRS comes with a comparable risk profile to frameshift mutations in breast cancer susceptibility genes PALB2 and CHEK2, and that the PRS strongly modifies breast cancer risk in the mutation carriers." (PMID 33318493, 2020). "We found that the mutation frequency of ERCC6 (1.8%) in breast tumors was similar to those of known breast cancer susceptibility genes, such as BRCA1 (2.9%), BRCA2 (2.9%), BLM (1.9%), FGFR2 (1.5%), and CHEK2 (1.0%)." (PMID 33277540, 2020). "Several mutations, including those in BRCA1, BRCA2, ATM, CHEK2, and PALB2, have been associated with the clinicopathological features exemplified by the breast cancer subtype and tissue of origin for additional cancers." (PMID 32566746, 2020). "To date, multiple breast cancer predisposition genes have been identified, mainly from studies of women of European ancestry, including BRCA1, BRCA2, PALB2, CHEK2, and ATM, which together accounted for 25% of the familial risk." (PMID 32318955, 2020).
breast cancer (continued). "We then compared the prevalence of breast cancer and other cancers in women with biallelic and monoallelic CHEK2 PVs." (PMID 31993860, 2020). "Biochemical analysis reveals, in addition to previously reported activation of PI3-kinase/Akt/mTOR pathway, PRR14 overexpression regulates cell cycle in breast cancer by inhibiting CHEK2’s activation, followed with the deregulation of DNA damage pathway." (PMID 32541902, 2020). "Homozygous CHEK2 c.1100del has, in fact, been reported in 14 female breast cancer cases in the Dutch population." (PMID 31993860, 2020). "There are twenty recurrent mutations in six breast-cancer-predisposing genes in Poland (BRCA1, BRCA2, CHEK2, PALB2, NBN, and RECQL)." (PMID 32824581, 2020). "Breast cancer frequency was higher among biallelic CHEK2 PV carriers (80.6%, 25/31) than monoallelic carriers (41.2%, 2668/6473; p < 0.0001)." (PMID 31993860, 2020). "Four Polish founder variants in CHEK2 (1100delC, IVS2+1G>A, del5395, and I157T) were described in TC patients who were also diagnosed with BC or had familial breast cancer history." (PMID 32443704, 2020). "We genotyped 2464 women with breast cancer diagnosed below age 41 years for twenty recurrent germline mutations in six genes, including BRCA1, BRCA2 CHEK2, PALB2, NBN, and RECQL." (PMID 32824581, 2020). "Other studies using multigene panels found that over 4% of women at risk of hereditary breast cancer had mutations in genes other than BRCA1/2, including PALB2, CHEK2, and ATM." (PMID 32090079, 2020). "For instance, genome-wide association studies performed by the Breast Cancer Association Consortium showed that BRCA2, CHEK2, ESR1, FGFR2, MDM4 and PIK3R3 carry germline variants associated with BC development." (PMID 32210335, 2020). "Pathogenic variants were identified in CHEK2, MUTYH, and RAD51B in four breast cancer patients, which represented 8.3% of the cohort." (PMID 31780696, 2019). "Estimates are that about 1.1–1.7% of women with breast cancer have a PV in CHEK2, 1.4–2.1% in BRCA1, 1.6–2.2% in BRCA2, 0.87–1% in ATM, and 0.84–0.87% in PALB2, with other genes less than 1%." (PMID 30832243, 2019). "Reported DSB repair variants in breast cancer comprise PALB2, NBN, RAD51, ATM, CHEK2, ATR, RAD50, and WRN." (PMID 31658756, 2019). "In conclusion, functional analysis suggest that two CHEK2 variants found in our cohort (p.Glu239Lys and p.Pro484Leu) are likely to affect CHK2 activity in vivo and be associated with increased risk of breast cancer." (PMID 31780696, 2019). "In contrast, mutations in the mismatch repair genes CHEK2 and CDKN2A collectively decreased from 4.89% to 2.52% in the context of personal history of breast cancer." (PMID 31497750, 2018). "In five patients (5 of 83; 6% of cohort), we detected causative pathogenic variants in established hereditary breast cancer susceptibility genes (i.e., PALB2, CHEK2, ATM)." (PMID 30086788, 2018).
breast cancer (continued). "It is worth mentioning that, in principle, the role of mutant ATM and CHEK2 as breast cancer genes is still debated." (PMID 29271107, 2018). "An additional 5.1% (95% CI: 2.4–8.5) are estimated to carry a pathogenic allele of a moderate-risk breast cancer susceptibility gene (i.e., ATM, BARD1, CHEK2, or NBN) bringing the total proportion of estimated carriers to 10.4% (95% CI: 6.5–14.9)." (PMID 29945567, 2018). "Cell cycle checkpoint kinase 2 (CHEK2) is a well-established moderate-penetrance breast cancer gene." (PMID 29338689, 2018). "Patients in the immediate reconstruction group significantly more often had a genetic predisposition to breast cancer (i.e., BRCA1, BRCA2, and/or CHEK2 mutations; p < 0.001) and a lumpectomy in their medical history (p = 0.032)." (PMID 29399731, 2018). "In the current study, CHEK2 protein-truncating variants were associated with a 3.8-fold increased risk for MBC, which is highly consistent with findings from the studies of breast cancer families." (PMID 28008555, 2017). "Other potential sources of DNA repair deficiency in breast cancer, also involving DSB repair processes, include germline mutations in DNA repair genes PALB2, FANCM, ATM, CHEK2 (and possibly also RAD51C) characterized as loss-of-function variants." (PMID 28679371, 2017). "As a proof of concept, known breast cancer-predisposing genes like BRCA1, BRCA2, and CHEK2 were selected by our procedure." (PMID 28569218, 2017). "We found IVS2 + 1G > A missense variant in a positive case of CHEK2 mutation IVS2 + 1G > A, which was associated with hereditary breast cancer and the other that was found to have a sporadic nature (2 out of 100 patients) (p = 0.48)." (PMID 28680382, 2017). "Known genetic factors contributing to a higher lifetime risk of breast cancer comprise rare variants in BRCA1, BRCA2, PALB2, ATM and CHEK2." (PMID 28199975, 2017). "Both patients had a family history of breast cancer and the carrier of CHEK2 had a secondary diagnosis of breast cancer herself." (PMID 28591191, 2017). "Most pathogenic mutations were in genes with an established breast cancer risk (ATM, BRCA1, CHEK2, and PALB2)." (PMID 28281021, 2017). "Similar to female breast cancer, the male CHEK2 c.1100delC carrier tumours were of ductal histology, ER positive, and poorly differentiated (grade 2–3)." (PMID 28874143, 2017). "CHEK2 gene is known as a tumor suppressor gene in breast cancer (BC), which plays a role in DNA repair." (PMID 28680382, 2017). "Additional breast cancer susceptibility genes including ATM and CHEK2 also require prospective data to provide the evidence-base for clinical decision making around risk management/reduction and treatment options." (PMID 27099641, 2016). "We have next studied the effect of CHEK2 down-regulation in stromal fibroblasts on the migration and invasion abilities of breast cancer MDA-MB-231 cells." (PMID 27484185, 2016). "The positive yield in CHEK2 among women with breast cancer (2.0%; 66/3,315) or endometrial cancer (1.5%; 7/453) were consistent with published frequencies." (PMID 26681312, 2016). "Podophyllotoxin blocks the growth of MCF-7 breast cancer cells by altering checkpoint kinase 2 (Chk-2) signaling pathway." (PMID 27877185, 2016).
breast cancer (continued). "On the other hand, ectopic expression of CHEK2 repressed the migratory/invasiveness abilities of active breast stromal fibroblasts as well as their paracrine effects on breast cancer cells." (PMID 27484185, 2016). "Germline mutations in DNA mismatch repair genes (BRCA1, BRCA2, CHEK2, ERCC4, FAAP100, and TP53BP1, amongst others) are associated with breast cancer susceptibility." (PMID 27608040, 2016). "A deletion in CHEK2 was investigated by the same group in 1071 breast cancer patients from 718 families with a positive history of breast cancer and no BRCA mutation, a population-based set of 636 patients, and 1620 controls." (PMID 27716388, 2016). "CHEK2 c.538C>T (p.Arg180Cys) was identified in 158 breast cancer cases and 142 controls in studies of white Europeans." (PMID 27595995, 2016). "The most frequently observed aberrations in CHEK2*1100delC breast cancers are those seen in many breast cancers of the luminal intrinsic subtypes." (PMID 26553136, 2015). "The CHEK2, TGFβ1, CASP8 and ATM genes belong to the ‘low to moderate-risk’ breast cancer susceptibility genes." (PMID 26124080, 2015). "In contrast to our BRCA1 profiling results, most of these CNAs in CHEK2*1100delC breast cancers are seen at very low frequencies and are marginally statistically significant." (PMID 26553136, 2015). "High resolution copy number and LOH profiling by means of SNP array analysis was performed to gain insight into the genomic characteristics of CHEK2*1100delC as compared to BRCAX breast cancers." (PMID 26553136, 2015). "With the exception of copy number loss of chromosomal arm 1p, which was found more frequently in CHEK2*1100delC breast cancers." (PMID 26553136, 2015). "Our analysis was restricted to breast cancers of the luminal intrinsic subtypes as CHEK2*1100delC breast cancers are found to be exclusively of these mRNA based subtypes." (PMID 26553136, 2015). "Combined with 16 studies, it showed that CHEK2 1100delC heterozygotes rate was 3- to 5-fold higher in the breast cancer group than the control group." (PMID 25674498, 2015). "Two double heterozygous breast cancer cases were identified in the TNBC group (one patient was BRCA1/CHEK2 and the other was BRCA1/NBN)." (PMID 26083025, 2015). "Compared to the BRCA1 and BRCA2 profiles reported in literature and our previous study, copy number aberrations are infrequently seen in CHEK2*1100delC breast cancers." (PMID 26553136, 2015). "We performed high-resolution copy number, LOH and gene expression profiling of CHEK2*1100delC breast cancers to better understand the tumorigenesis to which the germ line CHEK2 deficiency predisposes." (PMID 26553136, 2015). "DNA diagnostics for hereditary breast cancer is recently extended with the CHEK2 gene in the Netherlands and in the near future potentially also in other countries having a relatively high prevalence of CHEK2 mutations." (PMID 25958056, 2015). "We compared our results with previously reported findings on genomic and gene expression profiling of CHEK2*1100delC breast cancers." (PMID 26553136, 2015). "This includes the copy number loss of chromosomal arm 1p seen in CHEK2*1100delC breast cancers, and LOH/loss at the CHEK2 locus in only part of the tumors." (PMID 26553136, 2015). "As CHEK2*1100delC breast cancers are found to be exclusively of the luminal subtypes, the analyses were restricted to these intrinsic subtypes to avoid subtype associated confounding effects on copy number profiling." (PMID 26553136, 2015).
breast cancer (continued). "The copy number profiles of CHEK2*1100delC breast carcinomas were found to be heterogeneous and largely resemble those of the BRCAX breast carcinomas." (PMID 26553136, 2015). "To date, other low-penetrance genes, correlated with the risk of breast cancer, have been identified, such as ATM, BRIP1, CDH1, PALB2 and CHEK2." (PMID 24986639, 2014). "We report the identification of the first large duplication in the CHEK2 gene in a family with a history of breast cancer, detected during a study on hereditary breast cancer." (PMID 24986639, 2014). "Previously, we performed case-control mutation screening studies of ATM, CHEK2, XRCC2, and RAD51 to clarify our understanding of their role in breast cancer susceptibility." (PMID 24894818, 2014). "The first germline mutations identified in the CHEK2 gene were associated with Li-Fraumeni syndrome (MIM# 609265), a disease characterised by high occurrences of sarcomas, breast cancer, brain tumours, acute leukaemia and adrenocortical tumours." (PMID 24986639, 2014). "One of the three truncating CHEK2 mutations (IVS2 + 1G > A, 1100delC, del5395) was present in 9 of 420 women diagnosed with breast cancer (2.1%) and in 4 of 121 women (3.3%) with a history of breast cancer in a first- and/or second- degree relatives." (PMID 24713400, 2014). "We also show that VAAST 2.0 outperforms KBAC, WSS, SKAT, and variable threshold (VT) using published case-control datasets for Crohn disease (NOD2), hypertriglyceridemia (LPL), and breast cancer (CHEK2)." (PMID 23836555, 2013). "Several breast cancer susceptibility genes, such as BRAC1, BRAC2 and CHEK2, have been detected in recent decades." (PMID 24204725, 2013). "Genomic DNA from probands of 44 Ashkenazi Jewish high-risk breast cancer families (wild-type for BRCA1, BRCA2 and CHEK2) was sequenced." (PMID 22347400, 2012). "Mutations of CHEK2, PALB2, and BRIP1 have a 2.34, 2.3, and 2.0 fold increase risk for breast cancer compared to the normal population, respectively." (PMID 22606018, 2012). "Three previously reported breast cancer-associated variants, BRCA1 c.5095C > T, CHEK2 c.470T > C, and CHEK2 c.1100delC, were observed in eleven (13.4%) individuals." (PMID 21356067, 2011). "In the largest data set (Uppsala), the CHEK2 1100delC signature also significantly also predicted 10-year breast cancer-specific survival." (PMID 21542898, 2011). "Though first discovered in breast cancer patients, CHEK2 mutations have since been reported to predispose to a range of cancer types, including ovarian, prostate, kidney and colorectal cancers, supporting the hypothesis that CHEK2 is a multiorgan cancer susceptibility gene." (PMID 21569354, 2011). "In the largest dataset, the CHEK2 1100delC signature significantly predicted 10-year breast cancer-specific survival." (PMID 21542898, 2011). "Breast cancer risk is also influenced by rarer variants that confer moderate breast cancer risks such as ATM, CHEK2, BRIP1 and PALB2." (PMID 20146796, 2010). "Other breast cancer associated founder mutations (BRCA2, CHEK2, NBS1) were detected only in single patients." (PMID 19338682, 2009).